IGF1 (insulin like growth factor 1)
Diseases named in the same sentence as IGF1 in open-access papers (continued):
Sharing a sentence is not in itself a finding about the gene and the disease.
developmental delay (11 papers, 2012 to 2025). "Insulin-like growth factor-1 receptor (IGF1) gene haploinsufficiency on chromosome 15q26.3 is linked to reduced prenatal and postnatal growth, developmental delay, dysmorphic features, and skeletal abnormalities." (PMID 38591204, 2024). "Given plasma IGF1 deficiency in Arid1b+/- cohorts, we first tested if IGF1 replacement could rescue physical aspects of developmental delay and abnormal behavioral phenotypes." (PMID 28695822, 2017). "Moreover, we observed developmental delay of the small intestine and reduced growth associated with low circulating IGF1." (PMID 22326222, 2012). "He had severe rickets, metabolic acidosis, hypokalaemia, hypophosphataemia, and low IGF-1 levels at the age of three, in addition to his developmental delay." (PMID 37508663, 2023). "Consistent with the developmental delay in the liver Csf1rko rats had greatly-reduced circulating IGF1." (PMID 34081701, 2021). "The most predictive factors for IGF-1R deletion include small birth size, head size, and stature, as well as high IGF-1 levels, developmental delay, and micrognathia." (PMID 22587301, 2012). "Therefore, we speculate that high cortisol and low IGF-1 levels under HS may impair embryo implantation and development, leading to developmental delays." (PMID 40563258, 2025). "We observed significant beneficial effects of IGF-1 in a mouse model of ASD and of developmental delay." (PMID 23621888, 2013). "In summary, our results show that IGF-1, approved for use in children, can lead to functional improvements in a mouse model of ASD and developmental delay, representing an important preclinical step towards novel therapeutics." (PMID 23621888, 2013).
dilated cardiomyopathy (11 papers, 2010 to 2025). Cardiomyopathy which is characterized by dilation and contractile dysfunction of the left and right ventricles. "CACNA2D2 and IGF1 are associated with dilated cardiomyopathy pathway according to KEGG pathway enrichment analyses." (PMID 33392258, 2020). "The pathways for hypertrophic cardiomyopathy (P = 0.005), TGF-β signalling (P = 0.006), and dilated cardiomyopathy (P = 0.008) contained genes for integrins, IGF-1 and TGF-β2 and -β3." (PMID 25545425, 2015). "Another recent study showed that the lncRNA HAND2-AS1 may participate in end-stage dilated cardiomyopathy by interacting indirectly with IGF-1 (insulin-like growth factor 1)." (PMID 34445422, 2021). "The dilated cardiomyopathy (DCM) pathway involves proteins such as Desmin, DMD, Titin, Tnt, ACTA1, TPM, Laminac, SGCD, TNF-α, IGF-1, TGF-β, and Ang-II." (PMID 32419790, 2020). "Among the remaining 19 DEGs, IGF1 (NO.17), MYL2 (No. 31), PCK1 (No. 33) and PRKACA (No. 39) were involved in the pmAF – related PPAR signaling pathways, focal adhesion and dilated cardiomyopathy." (PMID 24204599, 2013).
Duchenne muscular dystrophy (11 papers, 2009 to 2024). Duchenne muscular dystrophy (DMD) is a neuromuscular disease characterized by rapidly progressive muscle weakness and wasting due to degeneration of skeletal, smooth and cardiac muscle. "Insulin-like growth factor-1 (IGF-1) has been considered as a therapeutic agent for muscle wasting conditions including Duchenne muscular dystrophy as it stimulates muscle regeneration, growth and function." (PMID 38189760, 2024). "IGF-1 is potentially useful in the management of Duchenne muscular dystrophy, muscle atrophy, and promotes neurite development." (PMID 32722232, 2020). "IGF-1 mediates the therapeutic effects of ASCs in Duchenne muscular dystrophy and dystrophic muscle diseases." (PMID 28854965, 2017). "In Duchenne muscular dystrophy, IGF-1 activates muscle growth and hypertrophy and appears to improve the loss of muscle mass." (PMID 29181033, 2017). "Ligation of the IGF-1 receptor by synthetic IGF-1 is used as a treatment for growth hormone insensitivity syndrome and has recently been explored as the therapeutic for neurologic diseases such as myotonic dystrophy type 1, Duchenne muscular dystrophy, and ALS." (PMID 35831747, 2022). "Since IGF-1 is secreted at a bioactive level by adipose tissue-derived mesenchymal stem cells (ASCs), these cells (ASCs) provide a therapeutic option for Duchenne Muscular Dystrophy (DMD)." (PMID 24575400, 2014). "In a clinical trial, patients with Duchenne muscular dystrophy given synthetic IGF-1 for 6 months demonstrated enhanced growth as compared to non-IGF-1-treated patients but did not exhibit improved walking distance." (PMID 35831747, 2022). "A mouse model of the fatal pediatric disease Duchenne muscular dystrophy (DMD) showed that TNF-mediated activation of JNK induces conformational changes in the insulin receptor substrate (IRS)-1, thereby disrupting downstream events after IGF-1/IGF-1 receptor binding." (PMID 35328423, 2022).
hypertrophic cardiomyopathy (11 papers, 2015 to 2025). A condition in which the myocardium is hypertrophied without an obvious cause. "“Hypertrophic cardiomyopathy” in the signal pathway was followed with the p.adjust value of 1.10×10-3 and the corresponding collective action gene set with mutations included 8 genes: IGF1, CACNA1S, MYH7, IL6, TTN, CACNB2, LAMA2, DMD." (PMID 37876543, 2023). "Endothelin-1, its membrane receptor and IGF1 gene expressions were significantly upregulated by T2D, leading to a predicting activation of concentric hypertrophic cardiomyopathy pathways (point A)." (PMID 38978010, 2024). "The GRS for lower FEV1/FVC specific to the hypertrophic cardiomyopathy pathway was associated with reduced liver enzymes (ALT and GGT) as well as lower apolipoprotein B, LDL, IGF-1 and mean platelet volume." (PMID 36914875, 2023). "Collectively, these observations suggest that excess GH/IGF-1 signaling results in hypertrophic cardiomyopathy and increased mortality." (PMID 35250583, 2022). "High amounts of collagen may lead to cardiac fibrosis whereas increased expression of IGF1 have been reported previously in hypertrophic cardiomyopathy." (PMID 31039163, 2019). "This study aimed to explore a potential link between hypertrophic cardiomyopathy (HCM) and serum IGF-1, 26S PSM, and 3-MH concentrations in cats." (PMID 40427314, 2025). "A recent study revealed increased IGF-1 concentrations in some non-diabetic cats diagnosed with hypertrophic cardiomyopathy (HCM)." (PMID 37756097, 2023). "This study investigates the metabolic effects of hypertrophic cardiomyopathy (HCM) in cats (n = 27; 13 cats in categories B1 + B2 and 14 cats in categories C + D) by analyzing serum concentrations of insulin-like growth factor-1 (IGF-1), 26S proteasome (26S PSM), and 3-methylhistidine (3-MH)." (PMID 40427314, 2025). "The explanation behind the development of hypertrophic cardiomyopathy in those patients is not yet determined, but it is thought to be due to high insulin concentrations that act through the insulin-like growth factor-I (IGF-1) receptor, which is also present in the heart." (PMID 38773407, 2024).
keloid (11 papers, 2020 to 2025). An irregularly shaped, elevated mark on the skin caused by deposits of excessive amounts of collagen during wound healing. "•CCNB1, EGFR, E2F8, BTG1, TP63, and IGF1 were associated with keloids." (PMID 39157347, 2024). "In keloids, growth factors, such as IGF-1 and TGFβ1, are closely associated with the pathogenesis of keloids, and fibroproliferation has been reported to be regulated—in part—by the ERK pathway, which is signaled by receptor tyrosine kinase phosphorylation by IGF-1." (PMID 32182995, 2020). "It is likely that elevated DPP4 levels in keloids inhibit the adipogenic capacity of IGF1, which can be restored by sitagliptin." (PMID 41395508, 2025). "A fibroblast-related diagnostic model for keloid based on a six-gene signature (CCNB1, EGFR, E2F8, BTG1, TP63, and IGF1) was proposed, showing high predictive accuracy in keloid diagnosis." (PMID 39157347, 2024). "In contrast, compared to the control group, protein levels of p-Akt and p-mTOR were significantly decreased in keloid fibroblasts from the IGF-1 + Wubeizi ointment-treated group and Wubeizi ointment-treated group (P < 0.05)." (PMID 33062677, 2020). "In contrast, compared to the control group, mRNA levels of Akt1 and mTOR were significantly decreased in keloid fibroblasts from the IGF-1+Wubeizi ointment-treated group and Wubeizi ointment-treated group (P < 0.05)." (PMID 33062677, 2020). "The mRNA levels of Akt1 and mTOR in keloid fibroblasts from the IGF-1+Wubeizi ointment-treated group was higher than those in keloid fibroblasts from the Wubeizi ointment-treated group (P < 0.05)." (PMID 33062677, 2020). "The results of western blot showed that, compared to the control group, phosphorylated protein levels of p-PI3K, p-Akt, and p-mTOR were significantly increased in keloid fibroblasts from the IGF-1-treated group (P < 0.05)." (PMID 33062677, 2020). "Compared to the control and Wubeizi ointment treated-group, mRNA levels of PIK3CA were significantly increased in keloid fibroblasts from the IGF-1+Wubeizi ointment-treated group and IGF-1-treated group (P < 0.05)." (PMID 33062677, 2020). "The results of qPCR showed that, compared to the control group, mRNA levels of PIK3CA, Akt1, and mTOR were significantly increased in keloid fibroblasts from the IGF-1-treated group (P < 0.05)." (PMID 33062677, 2020). "In the in vitro experiment, after the addition of IGF-1, the effect of Wubeizi ointment on inhibiting proliferation of keloid fibroblasts and promoting its apoptosis was diminished." (PMID 33062677, 2020). "In comparison to levels in control tissues, the expression levels of CCNB1, EGFR, BTG1, as well as TP63 were evidently lower in the keloid tissues (P < 0.05), while the expression levels of E2F8 as well as IGF1 were evidently higher in the keloid tissues (P < 0.05)." (PMID 39157347, 2024). "In the training dataset, the expression levels of CCNB1, EGFR, E2F8, BTG1, as well as TP63 were remarkedly lower in the keloid samples than in the control samples (P < 0.05); however, the expression of IGF1 was evidently enhanced in the keloid samples elative to the control samples (P < 0.05)." (PMID 39157347, 2024). "However, TGF-β1, along with insulin-like growth factor 1 and IL-1, can contribute to fibroproliferative disorders, such as keloids and hypertrophic scars." (PMID 39682531, 2024). "The established model based on CCNB1, EGFR, E2F8, BTG1, TP63, and IGF1 showed good performance and may be useful for keloid diagnosis." (PMID 39157347, 2024). "We used IGF-1, an agonist of the mTOR signaling pathway, to activate the mTOR signaling pathway after adding Wubeizi ointment, and then the proliferation of keloid fibroblasts was detected to test whether the drug efficacy is inhibited." (PMID 33062677, 2020).
keloid (continued). "Similarly, CD26 drives keloid fibroblast proliferation and invasion through IGF-1/IGF-1R-mediated PI3K/Akt/mTOR activation, promoting mTOR downstream effectors (P70S6K, 4E-BP1); inhibition of CD26 or IGF-1R abrogates these effects, underscoring their central role in keloid progression." (PMID 41424791, 2025). "An increase in IGF-1 leads to the expression of types I and III procollagen and the IGF-1 receptor was demonstrated to be overexpressed in keloid fibroblasts." (PMID 36483731, 2022). "Compared to the control and IGF-1-treated group, protein levels of PTEN were significantly increased in keloid fibroblasts from the IGF-1+Wubeizi ointment-treated group and Wubeizi ointment-treated group (P < 0.05)." (PMID 33062677, 2020). "Compared to the control and Wubeizi ointment-treated-treated group, protein levels of p-PI3K were significantly increased in keloid fibroblasts from the IGF-1+Wubeizi ointment-treated group and IGF-1-treated group (P < 0.05)." (PMID 33062677, 2020). "Compared to the control and IGF-1-treated group, mRNA levels of PTEN were significantly increased in keloid fibroblasts from the IGF-1+Wubeizi ointment-treated group and Wubeizi ointment-treated group (P < 0.01)." (PMID 33062677, 2020).
lymph node metastasis (11 papers, 2013 to 2025). "We found that the expression of IGF1 in PTC tissue samples was higher than that in adjacent normal specimens and was significantly associated with tumor size, TNM staging, and lymph node metastasis." (PMID 32851683, 2020). "Otherwise, Lan and colleagues demonstrated that genetic polymorphisms of insulin-like growth factor 1 (IGF-1) and interleukin-8 (IL-8) increased susceptibility to lymph node metastasis in CRC patients." (PMID 32284754, 2020). "The levels of IGF1 were significantly associated with tumor size, TNM staging, and Lymph node metastasis." (PMID 32851683, 2020). "Furthermore, IGF1 upregulation in CC was significantly associated with the TNM stage, distant metastasis, lymph node metastasis, and histological grade, except with age or tumor size." (PMID 34551673, 2021). "Moreover, IGF1 expression had positive effect on lymph node metastasis, distant metastasis, worse tumor differentiation, and higher AJCC stage." (PMID 34075028, 2021). "Furthermore, the levels of IGF1 were significantly associated with tumor size, TNM staging, and Lymph node metastasis." (PMID 32851683, 2020). "Up-regulation of lymphangiogenic factors like IGF1 may facilitate lymph node metastasis by promoting peritumoral lymphangiogenesis." (PMID 28624797, 2017). "Five genes (VEGFA, IFNB1, IGF1, TEK, and TGFBR1) are associated with angiogenesis, which provides clues to the mechanism of the association between epigenetic inactivation of CYB5R2 and lymph node metastasis." (PMID 26275421, 2015). "Several proangiogenic factors associated with interstitial hypertension-associated lymph node metastasis were identified in BxPC-3 and Capan-2 tumors, and three of these factors were up-regulated in high IFP/highly metastatic tumors in both models: TGFB, ANG, and IGF1." (PMID 28624797, 2017). "Similarly for patients with lymph node metastasis we identified four proteins, namely IL1α, XIAP, STX2, and SHKBP1, whereas for patients with liver metastasis we identified IGF1, IL1α, IGFBP2, MAML3, and SHKBP1 as significant." (PMID 24282616, 2013).
neuroendocrine tumours (11 papers, 2014 to 2025). "The present case describes a 34-year-old woman with a complex medical history, including a pituitary neuroendocrine tumor producing growth hormone and insulin-like growth factor 1, multiple skull-base surgeries, and an inactive CSF fistula." (PMID 41573480, 2025). "Octreotides are an analogue of natural somatostatine, inhibiting growth hormones and insulin like growth factor 1 and is used in gastrointestinal neoplasms and neuroendocrine tumours." (PMID 30336550, 2018).
ovarian tumor (11 papers, 2010 to 2025). "Whereas prospective studies reported a significant correlation between serum IGF1 levels and EOC risk among women younger than 55-years, other studies showed decreased serum IGF1 concentrations in postmenopausal patients with ovarian tumors." (PMID 34220714, 2021). "Two mechanisms have been postulated: increased total number of stem cells with subsequent increased chance of DNA mutations during cell division and/or raised insulin-like growth factor 1 (IGF1) (major determinant of height) and its link to a number of solid tumours including ovarian tumours." (PMID 35681688, 2022). "There is increasing evidence supporting a role for IGF-1 signaling in ovarian tumor progression." (PMID 20668531, 2010). "With isoflurane use, an increased expression of IGF-1 and IGF-1 RSKOV3 was found in ovarian tumor cells, which accelerated the cell cycle and proliferation." (PMID 35966857, 2022). "Insulin-like growth factor-1 (IGF-1), insulin-like growth factor binding protein-3 (IGFBP-3), leptin, the HOMA (hemostasis model assessment) score, fasting glucose, and calcium-125 can be used to differentiate between ovarian tumors and benign ovarian lesions." (PMID 41303820, 2025). "Taken together, we report for the first time that PON2 acts as a tumor suppressor in the early stage of OC by reducing IGF-1 production and its signaling, indicating PON2 activation might be a fruitful strategy to inhibit early stage ovarian tumor." (PMID 29531225, 2018). "Rictor was associated more with AKT1 rather than AKT2, and overexpression of Rictor facilitated IGF-1-induced AKT1 activation, whereas silencing of AKT1 but not AKT2 inhibited IGF-1- induced ovarian tumor cell migration." (PMID 22680924, 2012). "IGF-1 induced SKOV-3 ovarian tumor cell migration was abolished by the PI3K inhibitor LY294002 or by AKT inhibitors, whereas inhibition of ERK or mTORC1 did not affect IGF-1- induced SKOV-3 cell migration." (PMID 22680924, 2012).
papillary thyroid cancer (11 papers, 1995 to 2025). "The recent literature suggests a possible link between sustained IGF-1 stimulation and the pathogenesis of papillary thyroid carcinoma, the most prevalent subtype in our T2D cohort." (PMID 40731899, 2025). "The serum of differentiated thyroid cancer patients shows low levels of exosomal miR-130a-3p, which upregulates its target, insulin-like growth factor 1 (IGF-1)." (PMID 36612314, 2023). "METHODS: The serum levels of 25(OH)D, PDGF and IGF-1 were assessed in 70 patients with papillary thyroid cancer (PTC), 60 patients with benign thyroid nodules (BN) compared to 60 normal controls (NC) using ELISA technique." (PMID 32711436, 2020). "The case with a previous diagnosis of papillary thyroid cancer (2 cm diameter) was a male with a pituitary macroadenoma, diagnosed in 2013 with initial levels of IGF-1 of 894.2 ng/mL." (PMID 25127456, 2014). "Papillary thyroid carcinoma (PTC) occurred in 25% of the patients, who had significantly higher levels of IGF-1." (PMID 40088375, 2025). "The majority of papillary carcinomas showed weak to moderate epithelial positivity for IGF-1 mRNA and negative stroma." (PMID 7547225, 1995).